EGF (epidermal growth factor)
Diseases named in the same sentence as EGF in open-access papers (continued):
Sharing a sentence is not in itself a finding about the gene and the disease.
cancer (continued). "Cancer-associated fibroblasts (CAFs) can produce epidermal growth factor (EGF), hepatocyte growth factor (HGF), fibroblast growth factor (FGF), IL-6, IL-8, chemokine C-X-C motif ligand 12 (CXCL12), and matrix metalloproteases (MMP-3 and MMP-9)." (PMID 33406763, 2021). "This is due to the association of core fucosylation with TGFβ1, epidermal growth factor, and B cell receptors, as well as the uptake of drugs by cancer cells being dependent on the molecular interaction between cell surface proteins and drugs." (PMID 33466384, 2021). "The epidermal growth factor (EGF) family is closely associated with cancer; HER4 (ErbB4) is expressed in a series of isoforms owing to AS." (PMID 33996533, 2021). "Since VGCCs of different types have been associated with several cancers, the possible oncogenesis mechanisms are seemingly linked to calcium-dependent mitogenic signals of epidermal growth factor." (PMID 34557425, 2021). "ERK and PI3K/AKT are critical components of EGF-activated signaling, which has been associated with human cancer EMT." (PMID 32174831, 2020). "In bones, on the other hand, there is an increase in the expression of CCL3 in bone-marrow-derived monocytes caused by the secretion of epidermal growth factor (EGF) by cancer cells." (PMID 33076281, 2020). "The kinases MSK1 and MSK2 are linked to the epidermal growth factor-pathway while the p38/MSK1/CREB transcription was shown to have oncogenic potential in some types of cancer." (PMID 32466334, 2020). "A single nucleotide polymorphism (SNP) in the 5′ untranslated region of the EGF gene (EGF+61 A>G — rs4444903) has been associated with increased levels of EGF and consequently is a risk for cancer development of distinct tumors." (PMID 32881389, 2020). "Individuals with EGF mutations were shown to have associated isolated recessive renal hypomagnesemia and cancer patients treated with the EGFR inhibitor cetuximab have reduced serum Mg2+ levels that normalize upon therapy withdrawal." (PMID 32706027, 2020). "Activation of the Erk pathways and the cross-talk with EGF signals have both been proposed as the underlying mechanism of how periostin accelerates proliferation of cancer cells." (PMID 32000779, 2020). "Epidermal growth factor (EGF) induces sudden loss of PIP2 in membrane that activates local cofilin pool in membrane in carcinoma." (PMID 33172190, 2020). "MiR-7 targets and downregulates oncogenic factors in cancer-associated signaling pathways including EGF, Bcl-2, Raf1, and Akt/PI3K61." (PMID 30783079, 2019). "Small compounds accelerated and enhanced EGFR and associated proteins degradation during EGF and/or glutamine starvation of cultures, thereby demonstrating high potency in killing cancer cells by simultaneously modulating signaling and metabolic pathways." (PMID 31374910, 2019). "The overactivation of epidermal growth factor (EGF) receptor (EGFR) is implicated in various cancers." (PMID 30544639, 2018). "Endothelial cells secreted-EGF promoted the migration property of T-cadherin deficient cancer cells, which was found to be more sensitive to EGF response." (PMID 29455663, 2018). "There is crosstalk between the two pathways in EMT progression, as EGF treatment enhances IL-6 production, and elevated level of IL-6 is associated with cancer cell aggressiveness and metastasis by inducing EMT through activating STAT3 and Akt signaling." (PMID 28903339, 2017). "TGF-β can interact with other growth factors such as the epidermal growth factor (EGF) to influence the malignant transformation of CSCs as well as the activation of cancer-associated stromal fibrosis." (PMID 28245823, 2017). "Bisecting GlcNAc on N-glycoproteins is described in E-cadherin-, EGF-, Wnt- and integrin- cancer-associated signaling pathways." (PMID 27429195, 2016). "The unbiased screen identified several EGF‐responsive lncRNAs, which have previously been associated with cancer progression, demonstrating the suitability of our approach." (PMID 27485121, 2016).
cancer (continued). "Llgl1's role as a polarity regulator in the Scribble complex is important, and as we have shown, its loss results in an increase of cancer stem-cell like qualities, migration, and transplant survival in an EGF-dependent manner." (PMID 27542214, 2016). "As receptors for growth factors, including epidermal growth factor (EGF), aberrant signaling of tyrosine kinases has been associated with disease processes, including the development and spread of cancers." (PMID 27760157, 2016). "Activation of ErbB receptors in cancer occurs through various mechanisms, including mutation, amplification and regulation of epidermal growth factor (EGF)-family ligands and cross-talk with other signaling pathways." (PMID 26215578, 2015). "Six cancer-associated molecules (HB-EGF, EGF, EGFR, sCD26, VEGF, and Calprotectin) were investigated in this study." (PMID 25992884, 2015). "Different from other types of diseases, cancer is caused by a wide diversity of oncogenic mutations and environmental matrix and factors (such as vasculature activators like EGF or VEGF etc.)that support the transformations of normal cells into malignant ones." (PMID 28031929, 2015). "As the polymorphisms of the EGF gene affect the susceptibility to numerous types of cancer, the majority of the case-control studies on EGF genes have been conducted on exonic polymorphisms and untranslated regions (UTRs)." (PMID 24137467, 2013). "We are reporting the first clinical study of the wound healing risk associated with surgery after the use of the therapeutic cancer vaccine, CIMAvax® EGF." (PMID 24127898, 2013). "The IPA results revealed that several cancer-associated pathways, including EGF, FGF, mTOR, integrin, JAK/STAT, and ERK/MAPK signaling pathways, were overrepresented in the AA PCa versus CA PCa comparison." (PMID 23365759, 2013). "Polymorphisms of the EGF gene have also been shown to be correlated with several other types of cancer." (PMID 24137467, 2013). "The results revealed that the polymorphism was correlated with cancer in individuals carrying the G allele of the +61A/G polymorphism of the EGF gene." (PMID 24137467, 2013). "In this study, we have used an integrative high content analysis approach to identify the specific miRNAs implicated in EGF signaling in HeLa cells as potential mediators of cancer mediated functions." (PMID 23724959, 2013). "The majority of the remaining cancers still rely on some form of mutation in the epidermal growth factor (EGF) pathway." (PMID 22899907, 2012). "Based on this, the signaling mechanisms underlying the effect of EGF on promoting cancer cell migration were investigated." (PMID 22701712, 2012). "The PDGF signaling pathway was the most significant cancer associated pathway in the T/NB comparison, and the EGF signaling pathway was also dysregulated." (PMID 22280838, 2012). "Accordingly, the results of the present study showed that the migration-diminishing effect of cAMP-signaling counteracts the migration-inducing effect of EGF, suppressing a further hallmark of malignant tumors cells, which have undergone EMT." (PMID 22479362, 2012). "EGF and its receptor have been frequently associated with the progression of several forms of cancers including those of the breast." (PMID 22860018, 2012). "Our results show that loss of miR-204 promotes BDNF (or EGF)-induced cancer cell migration and invasion by activating AKT/mTOR pathway leading to Rac1 translocation and actin reorganization." (PMID 23285024, 2012). "Epidermal growth factor (EGF) signaling affects a variety of cellular processes linked to aggressive phenotypes of lung and other cancer cells, such as growth, invasion, and metastasis." (PMID 23028479, 2012). "This is significant as crosstalk between EGFR and BDNF receptor TrkB has been shown to induce cancer cell migration and response to EGF is a key step during cancer cell invasion and is directly linked with metastasis." (PMID 23285024, 2012).
cancer (continued). "GEP100, one of the guanine nucleotide exchanging factors (GEFs) for Arf6, has been implicated in EGF signaling and cancer invasion." (PMID 22701712, 2012). "Immunoblotting showed that EGF at 10 ng/ml caused down-regulation of E-cadherin in both carcinoma lines, which was consistent with the observed EGF-induced cell morphological changes." (PMID 22479362, 2012). "Previous studies have demonstrated that EGF stimulates carcinoma cell metastasis in vivo, and this is associated with the induction of integrin αvβ5-mediated cell migration." (PMID 22586492, 2012). "Their research finally showed that SphK1 is a convergence point of multiple cell surface receptors for three different ligands, LPA, EGF, and S1P, which have all been implicated in regulation of motility and invasiveness of cancer cells." (PMID 21936950, 2011). "Another targeting approach is to use targeting moieties, such as the epidermal growth factor peptide which targets mainly cancer cells, covalently linked to one of the component of the peptide/DNA complex." (PMID 21849058, 2011). "Cancer cells stimulate the invasion of macrophages by secreting colony stimulating factor-1 (CSF-1), which in turn causes the macrophages to stimulate invasion of the cancer cells by secreting epidermal growth factor (EGF)." (PMID 21307399, 2010). "According to Rosenthal's criteria, the link between EGF +61 G/A polymorphism and cancer is somehow plausible." (PMID 20487573, 2010). "One of the five tagSNPs in this region was in strong linkage disequilibrium (LD) with the untranslated A61G (rs4444903) EGF variant, earlier shown to be associated with risk for other forms of cancer." (PMID 19319135, 2009). "In summary, nuclear localization of GFs and RTKs of the FGF and EGF/Erb families in cancer cells seems to be associated with a bad prognosis for patient survival." (PMID 17049074, 2006). "Impairment of the epidermal growth factor (EGF) system has been implicated in the pathogenesis of different types of carcinomas." (PMID 15827558, 2005). "High EGF levels are associated with aggressiveness and poor prognosis in a variety of cancers." (PMID 40696566, 2025). "The critical issue is that the initial cellular morphology at the time of EGF administration frequently differs significantly from that at the end of the measurement protocol, introducing a significant source of error in cancer diagnostic applications that rely on precise capacitance measurements." (PMID 41294763, 2025). "Overexpression of EGF or mutations in its signaling pathway may lead to uncontrolled cell growth and contribute to the development and progression of cancer." (PMID 40226632, 2025). "The enhanced IQGAP1 membrane localization and oligomerization on the membrane surface in turn concentrates EGF pathway components to the membrane surface which may be associated with the increase EGF stimulation seen in cancer." (PMID 39357822, 2024). "To study whether this CGN variant induces EMT, we examined the molecular markers of epithelial to mesenchymal gene expression switch after EGF treatment in different cancer cells carrying CGN WT and variant." (PMID 38424547, 2024). "Finally, when it comes to the field of cancer cell biology, it is well‐accepted that self‐sufficiency in growth signaling is a hallmark of all cancer cells; we show here how cells achieve such self‐sufficiency for the prototypical GF system, that is, EGF/EGFR." (PMID 36856068, 2023). "For patients with epidermal growth factor (EGFR)-mutated cancers, EGFR inhibitors, including the third-generation tyrosine kinase inhibitor (TKI) osimertinib, significantly prolong progression-free survival and overall survival, and are the current standard of care." (PMID 37296959, 2023).
cancer (continued). "Since EGF can bind to receptors other than EGFR, such as ErbB2 (HER2), ErbB3 (HER3), and ErbB4 (HER4) across most cancer contexts, and is a key player in cancer metastasis, it is likely that the EGF-associated mechanisms driving EMT are distinct from those regulating MHC I expression." (PMID 38067396, 2023). "Indeed, upon Src constitutive activation or EGF-mediated activation, Caspase-8 is associated with the cellular membrane, allowing sustained migration in cancer cells." (PMID 37444381, 2023). "Moreover, growth factors such as TGFβ and EGF stimulate the invasive behavior of cancer cells and are implicated in various stages of the metastatic process." (PMID 38002335, 2023). "After screening 20 protein kinases in this work that may be associated with EGF-mediated metabolic regulation in cancer cells, we identify that only ERK1/2 is activated by the treatment of EGF." (PMID 35122791, 2022). "Because many protein kinases have been implicated for EGFR signaling pathways, we have carried out Luminex multiplexing assays to screen a set of EGF-associated signaling kinases that are proposed to control glucose metabolism and/or serine biosynthesis in various cancer cells." (PMID 35122791, 2022). "Recent studies have established a connection between deregulated EGF signaling and metabolic reprogramming, especially rewiring in aerobic glycolysis, which is also known as the Warburg effect and recognized as a hallmark in cancer." (PMID 35931120, 2022). "Considering that rpS6 is a downstream effector of both the ERK and the mTOR pathways linked to cancer development and metastasis, the mTOR-selective inhibitor rapamycin was used to investigate the involvement of the mTOR pathway in the EGF-mediated signalling transduction." (PMID 35884900, 2022). "EGF promoted cancers' development and spread and are linked to deregulation of the ERBB system." (PMID 35655917, 2022). "Furthermore, the receptor for EGF is an appropriate target as it is overexpressed in HT-29 cells and has been implicated in this type of carcinoma." (PMID 36591314, 2022). "Similarly, cancers with activating mutations in the EGF receptor signalling pathway can be selected by EGF‐free culture medium." (PMID 34033245, 2021). "In addition, vessel-associated macrophages assist the intravasation of cancer cells into vasculature through the secretion of epidermal growth factor, which it is crucial for EMT induction." (PMID 33129234, 2021). "Also, YB-1 has been implicated in promoting cancer proliferation via activating EGFR signaling in an exogenous EGF-independent manner." (PMID 34696665, 2021). "The dysregulation of EGF is also associated with the growth and progression of many cancers." (PMID 32051689, 2020). "This supports the hypothesis that EGF in the CMtx media is causing resistance, as similar results were observed in cancer cells treated with exogenous EGF and cetuximab." (PMID 32481658, 2020). "Integrated analysis of public databases and structural predictions indicated that the two affected individuals also had additional variants in genes including TGFB2, TRAP1, PARP1, and EGF, each potentially relevant to cancer risk alone or in conjunction with the SDHA variant." (PMID 30680959, 2019). "Herein, we demonstrated that SGSM2 is involved in EGF-induced E-cadherin endocytosis and is associated with E2-induced cancer cell migration, and SGSM2 might be involved in regulation of cytoskeleton dynamics." (PMID 30744493, 2019). "Recently, EGF has been associated with the initiation of EMT in many cancers." (PMID 29977916, 2018). "The recognition of biomarkers for therapy response is solitary part of deep attention, though mainly study to date has become unsuccessful to discover a relationship linking cancer-associated markers including cancer mutations and EGF expression and scientific response." (PMID 28969709, 2017).
cancer (continued). "Of relevance is the recent demonstration that the interaction of ITGβ4 and epidermal growth factor receptor (EGFR) is associated with poor prognosis in cancer patients since epidermal growth factor (EGF)-dependent signals stimulate ITGβ4-mediated migration of metastatic cells." (PMID 28512118, 2017). "The EGF 61A>G polymorphism (rs4444903) is a commonly functional SNP in the 5’ untranslated region of the EGF gene that results in higher EGF levels in individuals with EGF genotype G/G in comparison to the A/A genotype and affects individual susceptibility to various carcinomas." (PMID 29379593, 2017). "This mutational landscape might influence cancer cells response to EGF, Transforming Growth Factor β1 (TGFβ1) and stromal inflammatory calcium binding proteins S100A8/A9." (PMID 27655713, 2016). "Besides TGFβ1, the identification and functional verification of additional cancer or fibrosis-associated factors, EGF, FGF2 and PDGF-BB, further confirmed the functional relevance of the invasion signature." (PMID 26243655, 2015). "However, the molecular mechanism underlying upregulation of EGF-mediated Swiprosin-1 expression in cancer cells requires further study." (PMID 26079945, 2015). "To date, most studies investigating how the EMT is regulated in cancer have focused on specific protein-encoding genes or some signaling pathways, for instance epidermal growth factor (EGF), transforming growth factor (TGF)-β, and fibroblast growth factor (FGF)." (PMID 25863539, 2015). "In terms of wound regeneration, it is important to note that the administration of EGFR inhibitors (which block EGF as well as TGF-α signaling) for cancer treatment causes adverse cutaneous side effects, and in some cases interferes with wound healing in humans." (PMID 25360592, 2014). "A functional genetic polymorphism in the EGF gene characterized by a G>A transition has been described in the 5’-untranslated region (rs4444903), and has been subject of investigation in several studies involving different types of cancer." (PMID 25909813, 2014). "In summary, the possibility that in KRAS and BRAF mutant cancer cells differential signalling mechanisms that involve MEK supported the mutual exclusivity of these two mutations, lead to the target-specific cancer therapeutics in the form of monoclonal antibodies against EGF and VEGF receptors." (PMID 25361007, 2014). "Since metastasis is the major cause of death in ICC, elucidating the mechanisms underlying EGF-dependent cell migration could facilitate the development of novel anti-cancer strategies for ICC using miRNAs." (PMID 23922722, 2013). "Epidermal growth factor (EGF) may increase cell motility, an event implicated in cancer cell invasion and metastasis." (PMID 23554696, 2011). "The effects of EGF +61 G/A allele in various cancers were conflicting too." (PMID 20487573, 2010). "Furthermore, it has been shown that EGF can cause EMT in human cancer cell lines, indicating that more research is needed to determine whether ROS are necessary for EGF-induced EMT." (PMID 40801639, 2025). "Indeed, EGF signaling is essential for tumor-cell growth for several types of cancer, and it is linked to the epithelial–mesenchymal transition, in which epithelial cells are transformed into fibroblast-like phenotypes with high motility and invasive properties, contributing to cancer metastasis." (PMID 37241784, 2023). "Therefore, these analyses strongly suggest that NUAK1 is associated with the Akt activation downstream of the EGF-signaling in human cancers, supporting further studies to investigate whether targeting the NUAK1/Akt axis could be therapeutically beneficial." (PMID 38135881, 2023). "Some of these pathways are part of the EGF system signaling network, which becomes hyperactivated with various mechanisms (gain of function mutations, genomic amplification, chromosomal rearrangements and autocrine activation) and participates in cancer pathogenesis." (PMID 37873809, 2023).